Y_RNA (Y RNA )
Gene: Miscellaneous RNA gene on chromosome 5 (173,254,190 to 173,254,290, reverse strand). Ensembl gene ENSG00000201277.
Homologues: Orthologues: chimpanzee Y_RNA (100% identical), macaque Y_RNA (95% identical). Paralogues in human: RNY3 (93% identical), RNY3P1 (91% identical), Y_RNA (91% identical), Y_RNA (90% identical), Y_RNA (89% identical), RNY3P11 (88% identical), Y_RNA (88% identical), Y_RNA (87% identical), RNY3P5 (86% identical), Y_RNA (86% identical), RNY3P14 (85% identical), Y_RNA (85% identical), and 94 more.